BRAF (B-Raf proto-oncogene, serine/threonine kinase)
Diseases named in the same sentence as BRAF in open-access papers (continued):
Sharing a sentence is not in itself a finding about the gene and the disease.
tumor (continued). "Although a selective RAF inhibitor was recently approved by the Food and Drug Administration for the treatment of metastatic melanomas harboring BRAFV600E mutations, response rates to selective BRAF inhibitors vary between tumor types." (PMID 26750638, 2016). "Because PTC with the BRAF V600E mutation has aggressive tumor biology, it can be suggested that it shows higher expression of glutamine metabolism-related proteins." (PMID 27447554, 2016). "Mutational analysis of CTNNB1 and BRAF was performed in 110 and 112 human CP tumor samples respectively." (PMID 26927026, 2016). "As a poor prognostic mutation recognized widely, lots of researches reported the associations between BRAF mutation with primary tumor site, age, gender and differentiation grade." (PMID 27050078, 2016). "The observations of hormesis in MAPKs as a result of inhibition of BRAF oncogene are widespread: low doses of RAF inhibitors designed to cease tumour proliferation can cause a paradoxical activation of tumour cell activity through undesired MAPK up-regulation." (PMID 27898662, 2016). "In a Chinese CMM trial one of the patients’ tumor was tested positive for the BRAF mutation and treatment with vemurafenib was given." (PMID 27520988, 2016). "BRAF V600E mutation was present in 238 of PTCs (69.2 %) and was associated with an infiltrative tumor margin (87.8 %, p = 0.004) and conventional type (93.7 %, p < 0.001)." (PMID 27277113, 2016). "Previous studies have reported that matrix metalloproteinases (MMPs) were modulated according to the intensity of MAPK pathway activation which partly explained the mechanism of increased propensity of tumor invasion in PTC patients carrying BRAF mutation." (PMID 27703281, 2016). "Factors increasing the risk of CLNM include the following: tumor size >1 cm, aggressive variants of PTC, extra thyroidal extension, tumor multifocality, age >45 or <15 years, male gender, white race, familiality, BRAF V600 mutation." (PMID 27185169, 2016). "Synergistic rational anticancer combined protocols are presented depending on the tumour cell background, like resistance to individual treatments, BRAF mutation or BCL-2 overexpression." (PMID 27520705, 2016). "In recent years, the BRAF mutation has emerged as a molecular maker related to aggressive tumor behavior, such as tumor size, extrathyroidal extension, multifocality, lymph nodal metastasis, tumor recurrence and advanced stage in PTC." (PMID 27008708, 2016). "All patients had received prior anti-CTLA-4 therapy and a BRAF inhibitor if a V600 mutation was present in their tumor." (PMID 26767073, 2016). "The median age at detection of brain metastasis was 56.0 years in BRAF mutated tumours (range 35–71 years), 59.5 years in NRAS mutated tumours (range 35–76 years) and 69.5 years in BRAF wild-type tumours (range 40–75 years)." (PMID 27213536, 2016). "Other studies demonstrated that a higher proportion of BRAF mutant cells in PTC is associated with larger tumor size and lymph node metastasis." (PMID 27410688, 2016). "In the present study, we investigated intra- and inter-tumoral heterogeneity of RAS and BRAF mutations in 60 tumor areas from 18 CRCs." (PMID 27916952, 2016). "Specifically, BRAF mutation alone was associated with older patient age (≥ 45 years) (P = 0.042), larger tumor size (P = 0.032), extrathyroidal invasion (P = 0.012), advanced stage (P = 0.022), and higher MAICS score (P = 0.002)." (PMID 26943032, 2016). "For example, tumor A00021 had both AKT1 E17K (27.9%) and BRAF G469A (19.7%) mutations, and tumor A00026 had both BRAF D594G (26.7%) and PIK3CA E542K (15.6%) mutations." (PMID 26989027, 2016). "Tumours with a CIMP ‘high’ phenotype are thought to arise from sessile serrated adenomas and these tumours carry specific mutations in the BRAF gene reminiscent to those encountered in the KRAS gene in CIN tumours." (PMID 27279102, 2016).
tumor (continued). "The BRAF p.V600E mutation was detected in the tumor specimen and we recommended a BRAF inhibitor based on limited but encouraging clinical evidence." (PMID 27245685, 2016). "When all patients are considered, Class 0 tumours are significantly associated with MSI that is also strongly correlated with BRAF mutation." (PMID 27302369, 2016). "In the QUASAR trial, HER2 overexpression was observed in 17 of 811 (2.1%) KRAS/BRAF WT tumours compared with one of 421 (0.2%) tumours harbouring a KRAS or BRAF mutation (p = 0.01)." (PMID 26690310, 2016). "The BRAF mutated tumour showed strong cytosolic and membranous positivity for B-Raf also on immunohistochemical analysis." (PMID 26197800, 2015). "That particular patient's tumor harbored a sensitizing BRAF mutation and received vemurafenib after progression on ipilimumab therapy." (PMID 25164960, 2015). "The distribution of mutated BRAF amounts in samples with less (n = 107) or more (n = 368) than 80 % of tumor cells were significantly different (P < 0.05)." (PMID 26141748, 2015). "BRAF mutational status was concordant between different tumor foci in nine of the cases 12 (75%); all tumors were positive for the mutation in four cases, and all were negative in five cases." (PMID 25882744, 2015). "BRAF inhibition has been shown to increase immune reaction in the tumor microenvironment and is associated with high serum tumor necrosis factor level." (PMID 26152183, 2015). "The well-known mutual exclusiveness of KRAS and BRAF mutations was observed, and MSI was more prevalent in KRAS wild-type and BRAF mutated tumours." (PMID 25884297, 2015). "BRAF mutation is known to be associated with tumours occurring in females and we found that in this cohort was shown to be negatively correlated with male gender (coef = −1.54, z=−2.16, p=0.062)." (PMID 26097884, 2015). "In one set of 60 FFPE tumor samples (15 with BRAF mutations per Idylla), the Idylla and cobas results had an agreement of 97%." (PMID 26330075, 2015). "For BRAF V600E mutation in 17 metastatic CRCs, sensitivity, specificity and accuracy were all 100% between cfDNA and direct DNA sequencing of tumor FFPE specimens." (PMID 26452027, 2015). "BRAF mutations were detected in 28 (23%) of the tumours and PIK3CA mutations were seen in 22 (18%) tumours mainly in exon 9 (n = 18; 82%) with 4 mutations in exon 20 (18%)." (PMID 25884297, 2015). "A faster and simplified method for detecting BRAF mutations in FFPE tumor samples is the novel, fully integrated, real-time polymerase chain reaction (PCR)-based IdyllaTM system." (PMID 26330075, 2015). "While p.V600E is the most common mutation detected in many tumor types, more than 100 mutations within exons 11 and 15 of the BRAF gene have been reported in the Catalog of Somatic Mutations in Cancer (COSMIC) database, accessed on 03/10/15." (PMID 26498038, 2015). "A very recent development in tumour testing for LS is the use of IHC to detect BRAF V600E mutations, the performance of which has been demonstrated to varying degrees." (PMID 25910169, 2015). "The mutation detected is the most common BRAF mutation found in human neoplasia and results from a T to A transversion at nucleotide 1799." (PMID 25883647, 2015). "While intra-tumour heterogeneity with regard to mutations conferring resistance to BRAF inhibitors has been reported before, the study by the Peeper group is the first to highlight the possible complications for PDX studies." (PMID 26174485, 2015). "In multifocal PTCs, previous studies provided evidence that BRAF mutational status or subtypes of RET/PTC differed among tumor foci 7–10." (PMID 25882744, 2015). "Tumours with both BRAF mutation and MSI had the lowest risk for dissemination also marginally significant for lower risk for disease recurrence in stages II and III." (PMID 25884297, 2015).
tumor (continued). "On the other hand, patients with tumours harbouring both BRAF wild type and MSS presented a higher risk of disseminated disease, and disease recurrence in stages II and III compared with all other groups." (PMID 25884297, 2015). "Analysis of BRAF-mutant foci progressing via dysplastic stages to low- and high-grade carcinoma revealed a preferred sequence of events in mouse serrated tumor progression: following the initiating BRAF mutation, MAPK activity was only mildly enhanced." (PMID 26299805, 2015). "AS-PCR indicated that BRAF mutational status between the tumor foci was discordant in three (25%) and concordant in nine (75%) of 12 available cases." (PMID 25882744, 2015). "A total of 157 patients with diverse advanced cancers with known FFPE tumor tissue mutation status for mutations in at least one of the selected cancer genes, which included BRAF, EGFR, KRAS, PIK3CA, were enrolled." (PMID 25980577, 2015). "Currently, KRAS and BRAF mutations are routinely tested in tumor tissue by various methods for selection of anti-EGFR therapy in metastatic CRC patients." (PMID 26452027, 2015). "We found that barasertib was very effective in inhibiting tumor proliferation of both BRAF mutated and wt cells." (PMID 25623468, 2015). "Hypermethylation of the MLH1 gene promoter (32 out of 40 patients) and BRAF mutations (24 out of 40 patients) were limited to the patients with a MSI / EMAST tumor (p < 0.001 and p = 0.004 respectively)." (PMID 25884216, 2015). "In one PCC tumour (1/85) an activating BRAF mutation was identified (c.1799T>A; p.V600E, 1.2%, 95% CI = 0%–6.38%)." (PMID 25883647, 2015). "These processes include proteins involved in cell adhesion, bony reconstruction, tumor front, apoptosis regulation, cell cycle/cell proliferation, and epidermal growth factor gene and BRAF V600 E mutations." (PMID 26823641, 2015). "In Tunisia, where population is similar to Morocco, one study, including 51 patients with CRC, found out also just one patient with a BRAF somatic mutation and this tumor has a MSS status." (PMID 26104511, 2015). "We have further shown that DNA extracted and amplified from the collected CTCs enable BRAFV600E mutational analysis, the result of which match the BRAF status of the originating tumor." (PMID 25807549, 2015). "BRAF mutation status was available for 71 patients in Cohort II—42 patients had a BRAF mutation, whereas tumours of 29 patients were BRAF wild-type." (PMID 26484413, 2015). "In agreement with the possibility of differential functional roles of oncogenic KRAS and BRAF mutations during early stages of tumor development, significant correlations with molecular and clinical features have been identified." (PMID 26299805, 2015). "Of interest, the 2 samples in which Idylla but not cobas detected BRAF mutations (1 BRAF V600E mutation and 1 BRAF V600R mutation) contained less than 25% tumor cells." (PMID 26330075, 2015). "In case P2, the BRAF p.V600E (c.1799 T > A) mutant allele frequency (29 %) was consistent with the estimated tumor cellularity (41–60 %), suggesting KRAS p.G15S (c.43G > A) was present in a subpopulation of tumor." (PMID 26498038, 2015). "Although molecular genetic techniques are the standard method to detect BRAF mutations, it requires high tumor contents, special equipment and skilled operator." (PMID 25784606, 2015). "It thus appears that tumor initiation and/or progression by KRAS or BRAF not only depends on mutational activation in the tumor-initiating cell, but also on successful evasion of common tumor suppressing mechanisms in the mutated clone." (PMID 26299805, 2015).
tumor (continued). "In vitro data on a panel of tumor cell lines showed that cell lines with BRAF or RAS mutations were more likely to be sensitive to AZD6244." (PMID 26525348, 2015). "BRAF mutations occurred in 38% (142/376) of the tumor samples, including 128 (90%) V600E and 8 (6%) V600K." (PMID 26327518, 2015). "This subtype is invariably associated with MSI and a very high rate of BRAF mutations: 86 versus 69 % in other MSI tumours and 19 % or less in the general population." (PMID 26321889, 2015). "In this model, the methylation of TFAP2E was shown to increase significantly in CpG1 (coef = 0.260, z=2.16, p=0.022), and significantly decrease in CpG2 (coef =−0.258, z=−2.55, p=0.008) in BRAF mutated tumours." (PMID 26097884, 2015). "In contrast, BRAF mutations or MSI were less common in tumours from patients with disseminated disease or in those developing recurrence in disease stages II and III." (PMID 25884297, 2015). "Sorafenib also induces apoptosis in vitro and in vivo in tumor cells harboring BRAF and/or KRAS or NRAS mutations." (PMID 26299806, 2015). "NRAS and BRAF mutations have been reported traditionally to be nearly mutually exclusive in a single tumor with nevertheless rare exceptions of double mutants." (PMID 26204954, 2015). "In the same way, apparent anti-tumour activity was observed for patients with BRAF mutated CRC treated with a selective mutant BRAF inhibitor." (PMID 26366557, 2015). "Today, KRAS and BRAF mutational status is determined in the primary tumor tissues before treatment initiation, however several problems arise." (PMID 25902072, 2015). "IHC visualized differences in the growth pattern of BRAF V600E mutated cells, which appeared in a tumor-like manner or as disseminated cells." (PMID 25794135, 2015). "Overall, we found a clear difference in MGL ligand and thus tumor-associated glycan expression between cells that were wild-type for BRAF and those that harbor the BRAFV600E mutation." (PMID 26172302, 2015). "Other variants related to tumor biology included a homozygous BRAF p.V600E mutation in THJ-21T and heterozygous and homozygous frame-shift deletions of HDAC10 (p.H134Tfs) and CDKN2A (p.Q70Sfs), respectively, in THJ-29T." (PMID 26680454, 2015). "Targeting BRAF with RAF-selective inhibitors has demonstrated remarkable tumor shrinkage in those tumors with BRAF mutations." (PMID 25886620, 2015). "The relationships between BRAF mutation status, patient and tumor characteristics, RFS, and DSS were analyzed." (PMID 25712893, 2015). "Consistently, clinical studies revealed that human cancer patients with BRAF- or KRAS-mutated tumours have the worst therapy prognosis." (PMID 26168967, 2015). "The BRAFV600E variant, as the remaining mutations in the BRAF kinase domain, induces continuous stimulation of cell proliferation and tumor growth through activating phosphorylation of ERK." (PMID 26322273, 2015). "For each of the patients, the results of the qPCR analysis for BRAF mutation in the DNA extracted from CTCs matched the BRAF mutation status of the primary tumor." (PMID 25807549, 2015). "In univariate analyses, tumor deposits, BRAF mutation, number of LMs (≥4), bilobar LM distribution and extrahepatic metastases resection were significantly associated with shorter DFS." (PMID 25162714, 2014). "The results from this prospective cohort study further support an influence of sex and lifestyle factors on different pathways of colorectal carcinogenesis, defined by KRAS and BRAF mutation status of the tumours." (PMID 24918610, 2014). "Several assays for KRAS and BRAF mutations have been developed that involve DNA extraction from a single tumor tissue block, followed by a mutation-specific, polymerase chain reaction (PCR)-based assay or the sequencing of the relevant codons." (PMID 24765171, 2014). "BRAF inhibitors such as vemurafenib have been associated with some degree of tumor regression in a large percentage of BRAF mutant patients." (PMID 25275294, 2014).
tumor (continued). "BRAF mutations are more frequent in women, in right-sided tumours and are more often associated with lower differentiation grade, mucinous histology and, subsequently, a poor prognosis." (PMID 24918610, 2014). "This tumor contained a V600E BRAF mutation and was MLH1 hypermethylated, indicating that it was MMR-deficient and that our panel was also more sensitive for CRC." (PMID 25085081, 2014). "The BRAF V600E mutation status was analyzed in 187 tumor samples using the multiplex allele-specific PCR method." (PMID 24396464, 2014). "Since vemurafenib is indicated for the treatment of patients with BRAFV600E-positive unresectable or metastatic melanoma, the patient selection process should begin with BRAF mutational analysis of patients’ tumor tissues." (PMID 26328215, 2014). "Less common is the presence of BRAF mutations in micro-satellite stable (MSS) tumours, indicating poor prognosis in the latter." (PMID 25361007, 2014). "The receptor tyrosine kinases EGFR and ERBB2, the GTPases KRAS, NRAS, and HRAS, and the kinase BRAF are frequently mutated in cancers and can drive tumor proliferation." (PMID 24874471, 2014). "Three factors were found to be independent predictors of poor disease-free survival (DFS) by multivariate analysis: tumor deposits, BRAF mutation and bilobar LM distribution." (PMID 25162714, 2014). "In fact, this single mutation dramatically increases BRAF activity and accounts for more than 80% of all reported BRAF mutations in tumours and implicates the constitutive activation of BRAF." (PMID 25361007, 2014). "BRAF/NRAS wild-type tumours were also found to have a higher average mutation rate compared to BRAF/NRAS mutant tumours." (PMID 24752294, 2014). "Of interest, most NRAS (5 of 6) and all BRAF (3 of 3) mutations clustered in ICC tumour subtype and were mutually exclusive with KRAS (15.7%)." (PMID 24867389, 2014). "In tumours that have BRAF mutation [HR (95%CI)=0.81 (0.46, 1.43), p=0.47] and in NRAS mutants, low PTEN level did not significantly influence prognosis [HR 95%CI)=0.88 (0.29, 2.69), p=0.82]." (PMID 24830350, 2014). "BRAF V600E mutation detection in PTC demonstrated that the BRAF V600E mutation was present in ~63.6% of the tumor tissue samples, predominantly in those of PTC." (PMID 24396464, 2014). "Molecular characterization of the tumor demonstrated a well-described BRAF V600E point mutation and loss of CDKN2A/B." (PMID 25563358, 2014). "Our data are reminiscent of what observed in a recent report in which down-regulation of CCL2 after treatment with the BRAF inhibitor PLX4720 was associated with reduced tumor growth." (PMID 24980831, 2014). "Association of BRAF mutational status with clinicopathological parameters stratified according to tumor thickness." (PMID 24475086, 2014). "During tumor progression, after cells underwent other/additional molecular changes, the BRAF mutation is acquired or the amount of mutated protein increases in numerous cells leading to increased tumor growth and metastasis formation." (PMID 25526463, 2014). "We also performed categorized analysis using tumor deposits, BRAF mutation and bilobar LM distribution for DFS, and we found that a high PI (>2.945) was highly predictive of short-term DFS (P<0.001)." (PMID 25162714, 2014). "An important mechanism that has been identified in various tumor entities is mutation of the BRAF gene, which results in expression of a constitutive active B-Raf kinase and hence constitutive activation of ERK." (PMID 25152734, 2014). "In Cancer models: The identification of mutationally activated KRAS and BRAF alleles in several tumour models supports the importance of this signalling pathway in cancer progression." (PMID 25361007, 2014). "In men, all anthropometric factors except height were associated with an increased risk of BRAF wild type tumours, whereas in women, only bodyfat percentage was associated with an increased risk of BRAF wild type tumours." (PMID 24918610, 2014).